FAS (Fas cell surface death receptor)
Diseases named in the same sentence as FAS in open-access papers (continued):
Sharing a sentence is not in itself a finding about the gene and the disease.
colorectal cancer (continued). "FAS was constitutively expressed at high levels in normal human colon tissues, but its expression was often reduced in human colorectal cancer tissues." (PMID 25605245, 2015). "Our results suggest that the reduction in FAS level was due to increased MIR196B expression in colorectal cancer." (PMID 25605245, 2015). "MIR196B expression was up-regulated in colorectal cancer tissue, whereas FAS expression was down-regulated." (PMID 25605245, 2015). "In human colorectal cancer, literature and our data indicate that FAS acts a tumor suppressor, and tumor cells may use silencing of FAS expression as a mechanism to advance the disease." (PMID 35053524, 2022). "FAS is silenced by its promoter DNA hypermethylation in human colorectal carcinoma." (PMID 35053524, 2022). "Furthermore, anti-MIR196B up-regulated FAS expression and increased apoptosis in colorectal cancer cell lines." (PMID 25605245, 2015). "Our results suggest that the up-regulation of MIR196B modulates apoptosis in colorectal cancer cells by partially repressing FAS expression and that anti-MIR196B could be a potential candidate as an anti-cancer drug in colorectal cancer therapy." (PMID 25605245, 2015). "The decrease in FAS expression could be responsible for the reduction of apoptosis in colorectal cancer cells." (PMID 25605245, 2015). "Our results suggest that up-regulated MIR196B modulates apoptosis in colorectal cancer cells by partially repressing FAS expression and that anti-MIR196B could be useful as an anti-cancer drug in colorectal cancer." (PMID 25605245, 2015). "Therefore, FAS plays a key role in colorectal-cancer growth control carcinoma, and human colorectal cancer may use the silencing of FAS expression as a mechanism to progress and metastasize." (PMID 35053524, 2022). "Conversely, sequencing of PTPN13 exon 7, which could be involved in the regulation of FAS-related apoptosis, in 103 colorectal cancer samples did not reveal any mutation." (PMID 33322542, 2020). "Also in colorectal cancer, miR-196b repressed FAS expression modulating cell apoptosis." (PMID 29259267, 2017). "However, FAS expression is often reduced in metastatic human colorectal carcinoma." (PMID 25605245, 2015). "In colorectal cancer, SRSF7 promotes exon 6 skipping in FAS, resulting in a soluble Fas isoform that lacks the transmembrane domain." (PMID 41465349, 2025). "Upregulated pirin (PIR) facilitates colorectal cancer (CRC) survival by suppressing Fas‐mediated apoptosis in two ways, namely, the disruption of NFκB2‐driven FAS transcription and the attenuation of FAS membrane translocation and assembling." (PMID 38148593, 2024). "In colorectal cancer tissue, we showed that MIR196B up-regulation was mutually followed by down regulation of FAS expression." (PMID 25605245, 2015). "FasL expression was only observed in colorectal carcinomas, but FAS was constitutively expressed at high levels in normal human colon tissues." (PMID 25605245, 2015). "The reduction in FAS was not sufficient to induce apoptosis in colorectal cancer cells." (PMID 25605245, 2015).
viral infection (21 papers, 2011 to 2025). "In addition, the related pathways of virus infection disease, such as kaposi sarcoma-associated herpesvirus infection, human papillomavirus infection, and Epstein–Barr virus infection, were enriched, with FAS and TBK1 being identified as pivotal genes." (PMID 40423420, 2025). "Necroptosis can be triggered by activation of upstream cell death receptors, the tumor necrosis factor (TNF) receptor superfamily, Toll-like receptors (TLRs), T-cell receptors, interferon receptors, FAS (CD95), virus infection sensor, and some drugs." (PMID 35748782, 2022). "We also found increased expression of other co-inhibitory molecules (BTLA, FASLG, FAS, and IDO1) that are associated with the regulation of T-cell exhaustion during chronic viral infection." (PMID 32731586, 2020). "Thus, the frequencies of the FAS rs1800682 (A/G), FAS rs2234767 (G/A), and FASL rs5030772 (A/G) polymorphisms seem to have different patterns for each type of viral infection." (PMID 39859379, 2025). "FAS is related to apoptosis pathway, and TLR9 is related to virus infection, both of them are involved in pathogenesis of EBV,24, 25 we chose FAS and TLR9 for further study." (PMID 33434416, 2021). "Epstein–Barr virus infection can alter the m6A-modified epitranscriptome of host B cells and upregulate mRNA and protein levels of fas cell surface death receptor (FAS) but downregulate toll-like receptor 9 (TLR9), which are related to apoptosis and virus infection." (PMID 37671161, 2023). "CD8+FAS+ T cells were increased at the time of FIV inoculation in PLV when compared to SHAM cats, and this increase is inversely correlated with viral loads at one week PI suggesting an acute impact of these cells on the establishment of viral infection." (PMID 29677149, 2018). "This review examines FAS-mediated apoptotic and non-apoptotic signaling pathways, with particular emphasis on the mechanisms of apoptosis and inflammation induced by bacterial and viral infections." (PMID 40330016, 2025). "Apart from this similarity, different virus infection pathways owned their unique genes, with STAT1,RSAD2 and IRF9 in the influenza A pathway,IL-2RA,IL-2RB and CD40 in the HTLV-1 infection pathway, HCFC1, MAP3K7, SOCS3, IRF9, HMGN1, and FAS in the herpes simplex infection pathway." (PMID 35795668, 2022).
autoimmune disease (20 papers, 2013 to 2025). A disorder resulting from loss of function or tissue destruction of an organ or multiple organs, arising from humoral or cellular immune responses of the individual to their own tissue constituents. "AA is an autoimmune disease caused by T cells attacking hair follicles expressing FAS and its ligand (FASLG) on the perifollicular infiltrates." (PMID 39459398, 2024). "Other autoimmune diseases have been associated with SNPs in FAS and these include Hashimoto’s thyroiditis, systemic sclerosis, and multiple sclerosis." (PMID 35059842, 2022). "In the ethnicity stratification analysis, the results of our meta-analysis revealed diverse associations between the FAS −670 A/G and −1377 G/A polymorphisms and various autoimmune diseases in different ethnic groups." (PMID 31840751, 2020). "We strongly believe that our findings can help resolve many of the controversies of the association of FAS polymorphism and autoimmune diseases." (PMID 31840751, 2020). "In the FAS −670 A/G polymorphism, a significant association between FAS −670 A/G and the risk of autoimmune diseases was observed under the heterozygous genetic model (GG vs. GA: OR = 1.079, 95% CI 1.004–1.160, P=0.038)." (PMID 31840751, 2020). "The association between FAS −1377 G/A polymorphism and the risk of autoimmune diseases was observed in Asians (A vs. G: OR = 1.15, 95% CI 1.05–1.25, P=0.002) but not in Caucasians." (PMID 31840751, 2020). "Seven previous meta-analyses have analyzed the association between the FAS −670 A/G or −1377 G/A polymorphisms and some autoimmune diseases." (PMID 31840751, 2020). "Intriguingly, variants in FAS and increased TCR αβ double-negative T cells (DNTs, a hallmark of ALPS) have been identified in multifactorial autoimmune diseases, while FAS itself could play a potential role in carcinogenesis." (PMID 35059842, 2022). "In the TSA of association of FAS −1377 G/A polymorphism and autoimmune diseases risk, the sample size also reached RIS (4387) and the cumulative Z-curve crossed the conventional boundary, although the cumulative Z-curve did not cross trial sequential monitoring boundary in allelic model." (PMID 31840751, 2020). "In summary, our meta-analysis suggested that the FAS −670 A/G polymorphism might be associated with the risk of autoimmune diseases, especially in Caucasians and Asians, SLE, MS, SSc, and HT." (PMID 31840751, 2020). "The FAS −1377 G/A/ polymorphism might be associated with the risk of autoimmune diseases, specifically for Asians and high quality studies." (PMID 31840751, 2020). "In the FAS −1377 G/A polymorphism, our results indicated that FAS −1377 G/A polymorphism was associated with the risk of autoimmune diseases (A vs. G: OR = 1.11, 95% CI = 1.03–1.20, P=0.008; AA vs. GG: OR = 1.23, 95% CI = 1.03–1.47, P=0.024; AA+AG vs. GG: OR = 1.14, 95% CI = 1.02–1.26, P=0.015)." (PMID 31840751, 2020). "However, the association between FAS −1377 G/A polymorphism and the risk of autoimmune diseases was observed in high-quality studies (A vs. G: OR = 1.14, 95% CI 1.05–1.24, P=0.002) but not in low-quality studies." (PMID 31840751, 2020). "Moreover, somatic FAS mutations could potentially underlie several cases of multifactorial autoimmune diseases such as SLE, which may display clinical and immunological features that are superimposable to ALPS." (PMID 35059842, 2022). "Fifth, autoimmune diseases are multifactorial diseases caused by interactions between genetic and environmental factors, meaning that the FAS −670 A/G and −1377 G/A polymorphisms may only partially influence the pathogenesis of autoimmune diseases; this may lead to bias in the present results." (PMID 31840751, 2020). "Similarly, this may explain why the FAS −670 G allele was associated with an increased risk of autoimmune diseases in Caucasians and with a decreased risk in Asians." (PMID 31840751, 2020).
autoimmune disease (continued). "Moreover, the FAS −670 A/G polymorphism might be associated with the risk of autoimmune diseases in Asian patients with SLE or AIH and Caucasian patients with SLE, MS, or SSc." (PMID 31840751, 2020). "Mouse model investigations indicated that FAS or FASL mutations could initiate autoimmune diseases." (PMID 24348139, 2013). "Finally, study numbers and sample sizes were relatively small in the stratification analysis by ethnicity, which may have resulted in inadequate statistical power to detect associations between the FAS −670 A/G and −1377 G/A polymorphisms and autoimmune diseases." (PMID 31840751, 2020). "In the TSA of association of FAS −670 A/G polymorphism and autoimmune diseases risk, the cumulative Z-curve neither crossed conventional boundary nor trial sequential monitoring boundary, however, the sample size reached RIS (3365) in allelic model." (PMID 31840751, 2020). "Indeed, research in the last 10 years revealed that single-nucleotide polymorphisms (SNPs) in FAS or FASL may correlate with some types of cancer and multifactorial autoimmune diseases." (PMID 35059842, 2022). "On the basis of quality score, the stratified meta-analysis suggested that the FAS −670 A/G polymorphism might not be associated with autoimmune diseases in high- or low-quality studies." (PMID 31840751, 2020). "Additionally, the results of the association between FAS −1377 G/A and autoimmune diseases risk did not change when the HWE-deviating studies were excluded in five models." (PMID 31840751, 2020). "The present results indicate that the FAS −670 G allele is associated with a decreased risk of SLE, MS, and AIH (in Asians), which conflicts with a previous finding that the FAS −670 G allele in the FAS promoter was associated with an increased risk of autoimmune diseases." (PMID 31840751, 2020). "Regulatory T cell dysfunction in the thymus, dysregulated expression of FAS (CD95) and anti-malarial drug usage resulting in symptoms such as muscle weakness are some other speculated mechanisms defying the association between the two autoimmune diseases." (PMID 32642338, 2020). "We found, for example, that Cluster 7 represents a set of genes annotated by terms related to autoimmune disease and pathogen response, and contains a number of genes that mediate tissue interactions with the immune system, including INFG, IL2, IL2RB, and FAS." (PMID 29176608, 2017). "The FAS -670A/G and FASL -124A/G polymorphisms were associated with autoimmune disease in European and Egyptian subjects but not with hepatitis B in a population from Iran." (PMID 36671466, 2022). "In addition, some of these genes have been described previously as biomarkers of one or a variety of autoimmune diseases, such as IFN-induced protein 44-like, chemokine receptor 1 and FAS." (PMID 25466291, 2014). "The essential role could be played by the FAS/FASL system in the maintenance of immune tolerance, and inhibition of autoimmune disease has been clearly established." (PMID 24348139, 2013).
gastric cancer (20 papers, 2010 to 2025). A primary or metastatic malignant neoplasm involving the stomach. "This case-control study found that each of a high glycemic index, high glycemic load, and FAS rs6586161 polymorphism of AA type increased gastric cancer risk." (PMID 37513656, 2023). "Conclusively, the risk of gastric cancer was increased for patients with a high glycemic index, high glycemic load, and the AA type of FAS rs6586161 polymorphism, respectively." (PMID 37513656, 2023). "Both the high glycemic load and AA type of FAS rs6586161 polymorphism increased gastric cancer risk; however, the interactions between these two elevated the risk of gastric cancer even more." (PMID 37513656, 2023). "As a result of comparing the association with the FAS rs6586161 polymorphism and gastric cancer risk, the AA type had a higher gastric cancer risk than the TT type or TT+TA type in the recessive model." (PMID 37513656, 2023). "According to previous studies, rs6586161, one of the SNPs involved in the FAS pathway, was reported to cause gastric cancer by showing an association with the AKT signaling pathway." (PMID 37513656, 2023). "This research investigated gastric cancer risk with regard to the glycemic index, glycemic load, and FAS rs6586161 polymorphism." (PMID 37513656, 2023). "For FAS rs6586161 polymorphism, increased gastric cancer risk was observed for the AA type compared to the TT type (OR = 1.95, 95% CI = 1.13–3.39)." (PMID 37513656, 2023). "The AA type, corresponding to the minor allele, causes problems with the function of FAS-mediated apoptosis, which increases the incidence of gastric cancer by failing to inhibit the activation of gastric cancer cells." (PMID 37513656, 2023). "Therefore, the purpose of this case-control study was to investigate the association between FAS rs6586161 polymorphism, carbohydrate consumption, glycemic index, and glycemic load with gastric cancer risk." (PMID 37513656, 2023). "Moreover, gastric cancer risk was more elevated for individuals who had the AA type of FAS rs6586161 polymorphism with a high glycemic load." (PMID 37513656, 2023). "Furthermore, we examined how the interacted association of glycemic load, which considered both quality and quantity of carbohydrate consumption, and FAS rs6586161 polymorphism affected gastric cancer risk." (PMID 37513656, 2023). "Furthermore, gastric cancer risk was significantly elevated for the participants with the highest glycemic load and AA type of FAS rs6586161 polymorphism (vs. the lowest glycemic load and TT type, OR = 5.53, 95% CI = 2.01–15.21)." (PMID 37513656, 2023). "Similarly, in gastric cancer, inhibition of FAS-mediated apoptosis was linked to an overexpression of the cluster-related miR-106a which was shown in cell lines but also in FFPE samples." (PMID 24955218, 2014). "Furthermore, the risk of gastric cancer was significantly increased for participants with the interaction of the highest glycemic load and AA type of FAS rs6586161 polymorphism compared to participants with the lowest glycemic load and TT type of FAS rs6586161 polymorphism." (PMID 37513656, 2023). "FAS deletions have been observed in many cancers, including prostate, colorectal, and gastric cancers, but the exact prevalence is not well known because previous studies have typically used small sample sizes." (PMID 39416461, 2024). "A significant inverse correlation was also found between miR-106a and FAS expression in gastric cancer cell lines and specimens." (PMID 37627777, 2023). "Gastric cancer is another type of tumor that shows a connection between high expression of FAS mRNA and better survival in this study." (PMID 31942177, 2020). "In contrast, it has been reported that FAS signaling promotes gastric cancer progression by activating STAT3 signaling." (PMID 32963220, 2020). "The FAS mRNA expression was also related to the PFS in gastric cancer (HR: 0.62 [0.5, 0.75], p=2.30e-06)." (PMID 31942177, 2020).
gastric cancer (continued). "The upregulated expression of numerous death receptors (TNFR1, TNFR2, and FAS) suggested that BF-rTK/GCV induced tumor cell apoptosis by death receptors signaling pathway in gastric cancer." (PMID 27275821, 2016). "As a high-glycemic-load diet can influence inactivation of the FAS pathway, the combined effects of the AA type and a high glycemic load can lead to negative synergy, significantly increasing the risk of gastric cancer." (PMID 37513656, 2023). "Research on the interactions between glycemic load and FAS rs6586161 polymorphism in relation to the risk of gastric cancer has not been previously published, to the best of our knowledge." (PMID 37513656, 2023). "Hence, the role of FAS in gastric cancer remains controversial." (PMID 31942177, 2020). "In addition, it has been reported that the miR-23a/b17 and miR-106a18 could target FAS to promote thymic lymphoma and gastric cancer progression, respectively." (PMID 32963220, 2020). "In AGS gastric cancer cells, we observed consistent 1.3-8-fold up-regulation of pro-apoptotic genes such as BAD, BAX, BID, and FAS after control lettuce and lettuce fortified with organic iodine, as compared to negative control." (PMID 36296971, 2022). "The aim of our study was to evaluate potential associations between the presence of gastric cancer (GC) and high risk atrophic gastritis (HRAG) and polymorphisms of genes encoding Angiotensin converting enzyme (ACE), Nod-like receptor 1 (NOD1), Toll-like receptor 4 (TLR4) and FAS/FASL." (PMID 21864388, 2011).